ALDH1A1 (aldehyde dehydrogenase 1 family member A1)
Diseases named in the same sentence as ALDH1A1 in open-access papers (continued):
Sharing a sentence is not in itself a finding about the gene and the disease.
tumor (continued). "Conversely, knockdown of ALDH1A1 in an orthotopic mouse model (from both taxane- and platinum-resistant cell lines) sensitized the tumors to treatment, resulting in reduced tumor growth." (PMID 30042330, 2018). "Primary tumor location should therefore be taken into consideration in the design of clinical studies testing ALDH1(A1)-targeting drugs." (PMID 30308036, 2018). "Collectively, these findings suggest the existence of a dynamic cross talk between tumor breast cells and the endothelium, favored by tumor ALDH1A1 expression which facilitates endothelial cell recruitment in a VEGF-dependent manner." (PMID 30541574, 2018). "In mice, significant reduction in the tumor-initiating ability of MCF-7/ER36 cells with ALDH1A1 depletion by shRNA was observed." (PMID 29393296, 2018). "This indicates that tumor cells increase their levels of ALDH1A1 in response to treatment and/or that high levels of ALDH1A1 make tumor cells less responsive to treatment, resulting in their therapy-induced selection." (PMID 30308036, 2018). "The results unraveled a decrease in the tumor growth in the xenografts derived from ALDH1A1-silenced cells in comparison to the respective xenografts from cells nucleofected with negative siRNA." (PMID 29902974, 2018). "ALDH-H exerted CSC-like properties such as drug resistance, colony/sphere formation, and enhanced tumor growth along with high levels of CSCs markers compared to ALDH1A1-low (ALDH-L)." (PMID 30166520, 2018). "ALDH1A1-expressing CSCs from breast, lung, head and neck squamous cancer, possess tumour-initiating capabilities, suggesting a role in supporting tumour proliferation and maintenance." (PMID 29568377, 2018). "Further insight on the ALDH1A1 mechanism as a driver of tumor progression was gained by examining two signalling pathways, i.e. retinoic acid and HIF-1α." (PMID 30541574, 2018). "Further, to study ALDH1A1 involvement in tumor angiogenesis, we examined tumor blood supply, monitoring the vascularity of the entire tumor volume by 3D Power Doppler imaging Visualsonic Vevo 2100." (PMID 30541574, 2018). "ALDH1A1 levels were significantly higher in patients that received radio- and/or chemotherapy prior to tumor resection." (PMID 30308036, 2018). "The potential role of ALDH1A1 in mediating the angiogenic phenotype in breast CSCs and tumor neovascularization is less known." (PMID 30541574, 2018). "The staining index for ALDH1A1 and Ki67 was generated for all the cells present within the tumor islands." (PMID 30287850, 2018). "While ALDH1A1 and MYC genes were reported in metastasis of several tumor types and associated with poor prognosis, for CCNG2, a cell cycle checkpoint cyclin upregulated in response to DNA damage, the association to stemness was not clear." (PMID 28938627, 2017). "Of note, the E107G mutant form of ALDH1A1 restored tumor growth to the same extent as the wild type ALDH1A1." (PMID 28978015, 2017). "Alcohol consumption increased ALDH1A1 protein levels in both control and tumor mice compared to their water-drinking counterparts." (PMID 29245988, 2017). "This was shown to be a result of dramatic decrease in the expression of atRA synthesizing enzymes ALDH1A1 with concomitant increase in atRA degrading enzyme CYP26A1 in intestinal tissues from tumor-bearing compared to tumor-free mice." (PMID 28098786, 2017). "Of these isoforms, ALDH3A1 was found to be the predominant isoform that was expressed in the primary tumor samples, and this expression was at a much higher level than that of ALDH1A1 or ALDH2." (PMID 28881734, 2017). "In tumours formed after injection of DCIS‐control cells into the mammary fat pad, dispersed ALDH1A1+ cells were detected predominantly in the tumour interior." (PMID 28707729, 2017). "ALDH1 levels in paraffin-embedded tumor tissues from 158 TNBC patients were evaluated by immunohistochemistry staining using an ALDH1A1 primary antibody." (PMID 28383433, 2017).
tumor (continued). "To evaluate the potential function of ALDH1A1 and ALDH3A1 in cell proliferation and tumor growth, we knocked out ALDH1A1 and ALDH3A1, both together (DKO) and individually (1A1_KO or 3A1_KO)." (PMID 28978015, 2017). "Most significantly, IHC analysis showed that Aldh1a1 is highly expressed tumor formed in mice injected with E10-TAZS89A-T cells." (PMID 28415606, 2017). "We detected large clusters of ALDH1A1+ cells in the interior portion of the tumour, as well as at the tumour periphery, in DCIS‐SOX11 tumours." (PMID 28707729, 2017). "The immunohistological analysis showed that these tumors resembled the original SCS histology and that only a small portion of tumor cells (<5%) expressed high levels of ALDH1A1." (PMID 27292183, 2016). "Overall, 20/27 (74%) tumor specimens that showed high BMI1 expression also showed high expression of ALDH1A1." (PMID 26770215, 2016). "ALDH1A1 and CD133 were also associated (P = 0.003); 21/31 (68%) tumor samples that were classified as having high ALDH1A1 expression were also positive for CD133 expression." (PMID 26770215, 2016). "One IHC study reported that a lower ratio of the ALDH1A1 level in adjacent mucosa to that of the tumor tissue (RA/C <1) positively correlated with tumor invasion and metastasis capabilities." (PMID 27152521, 2016). "As shown, PXR and ALDH1A1 were significantly correlated in primary tumor samples from stage II & III CCR patients (n=78) and in CRC liver metastatic samples (n=12)." (PMID 27448961, 2016). "This decrease in tumor outgrowth was accompanied by a decrease in Cyp1b1, Aldh1a1, and Sox2 expression, further linking AHR activity to expression of these genes." (PMID 26984638, 2016). "To re-test positive association between EMT and CSC markers mRNA expression levels in the primary tumors, measured by RT-qPCR, possible associations between BMI1, ALDH1A1, and CD133 protein expression levels in the primary tumor, measured by IHC, were tested." (PMID 26770215, 2016). "In other neoplasms, ALDH1A1 has been shown to correlate either with favorable or poor prognosis depending on the tumor setting or on tumor sample sets." (PMID 27724856, 2016). "Our CLM samples showed >97–99% tumor cell homogeneity on IHC, and the mean fold increases in ALDH1A1 and IGFBP1 after normalization to β-actin expression were 6.2 and 3.1, respectively, relative to the adjacent normal liver tissues." (PMID 27152521, 2016). "We previously demonstrated that ALDH1A1 is a human tumor antigen and that ALDHpositive cells can be targeted for eradication by ALDH1A1 - specific cytotoxic T cells." (PMID 27074569, 2016). "In vivo imaging revealed that mice inoculated with AhR + Aldh1a1 knockdown cells had reduced tumor burden and enhanced survival than those receiving Aldh1a1-expressing sh-AhR cells." (PMID 26242870, 2015). "CRC patients with circulating tumor cells expressing ALDH1, survivin and MRP5 have shorter PFS, and ALDH1A1 rs1342024 polymorphism associates with shorter time to tumor recurrence." (PMID 25788273, 2015). "Patients who had ALDH1A1 overexpression, in which tumor cells displayed high invasiveness, had poor OS and shorter RFS." (PMID 25253129, 2014). "In the high tumor invasiveness subgroup, patients with ALDH1A1 overexpression were prone to death (P < 0.001) and relapse (P < 0.001)." (PMID 25253129, 2014). "Specifically, higher ALDH1A1 expression means greater tumor size, higher SBR grade, greater possibility of LNM, higher expression of HER2, and lower expression of ER and PR." (PMID 24938375, 2014). "It is well known that ALDH1A1 can be used as a marker for breast CSCs, which have high tumor-initiating and self-renewal capabilities." (PMID 24938375, 2014). "Multicenter prospective studies based on large, homogeneous patient populations will be required to assess the relationship between tumor size and ALDH1A1 expression." (PMID 24938375, 2014).
tumor (continued). "In NTCU-induced SCC-bearing mice, tumor expression of ALDH1A1, CD133, and CD15 measured by immunohistochemistry was significantly increased following sunitinib treatment." (PMID 24500694, 2014). "ALDH1A1 expression was present in 78.9% (195/247) of the tumor samples, but only in 32% of the samples from normal and adjacent non-tumor tissues." (PMID 24485040, 2014). "ALDH1A1 also was found in both the patient tumor and xenografts derived from LUCA22 as well as metastases to the lung." (PMID 24324581, 2013). "ALDH1A1 expression characterizes a subpopulation of cells with tumor-initiating or CSC properties in several malignancies." (PMID 22710732, 2012). "The expression and activity of ALDH1A1 is tumor type-dependent, as seen from immunohistochemisty, Western blot analysis, and the Aldefluor® assay." (PMID 22852552, 2012). "Being a member of aldehyde dehydrogenases protein family, ALDH1A1 plays important role when expressed in a subpopulation of cells with tumor-initiating properties in a variety of malignancies and thus a possible candidate biomarker in cancer therapy." (PMID 23319948, 2012). "There was a strong association between ALDH1A1 positivity and the HER2 subtype in ER- disease with 38% of ALDH1A1 positive tumours being of the HER2 subtype compared to 18% of ALDH1A1 negative cases (P = 0.001)." (PMID 22112299, 2011). "Both ALDH1A1 and ALDH1A3 were associated with positive HER2 status where 26% of tumours positive for either marker were HER2 positive and 11% of negative cases were HER2 positive (P < 0.0001)." (PMID 22112299, 2011). "The assumption that ALDEFLUOR positivity of tumour cells correlates with ALDH1A1 expression by IHC has been questioned." (PMID 22112299, 2011). "This relationship was strongest amongst ALDH1A1 positive tumours where 73% of positive cases were also Ki67 positive whereas just 51% of negative cases were Ki67 positive (P = 0.003)." (PMID 22112299, 2011). "Low expression of ALDH1A1 was found to be an independent prognostic marker for overall survival (p = 0.004) in addition to AJCC tumour stage (p = 0.013) and treatment with adjuvant chemotherapy (p = 0.0001)." (PMID 21708005, 2011). "Staining of ALDH1A1 was mainly concentrated to < 10% of tumour cells in 3/5 poorly differentiated PC specimens." (PMID 19216797, 2009). "TaqmanTM qRT-PCR studies of UM-C6 tumor cells verified that ALDH1A1 gene expression was reduced 88% versus Luciferase-targeted shRNA transduced control cells, whereas neither ALDH3A1 nor ALDH5A1 gene expression were altered." (PMID 18560594, 2008). "Compared to vehicle-treated, ALDH1A1-targeted shRNA containing tumors, the difference in tumor volumes between CPA and vehicle-treated groups significantly differed by day 10 (n≥5, P = 0.0061)." (PMID 18560594, 2008). "This study clarified that IL-8-derived tumor cells could upregulate ALDH1A1 expression by activating the NF-κB signaling pathway, promoting tumor progression." (PMID 40008905, 2025). "The results showed that ALDH1A1 was upregulated in tumor tissues than in adjacent tissues." (PMID 40008905, 2025). "This potent effect is attributed to the selective accumulation of FeO NPs-DE in tumor tissues, inducing iron-dependent ferroptosis that was potentiated by the inactivation effect of DE on the glutathione system and ALDH1A1 activity-mediated stemness, as well as its apoptotic activity." (PMID 39888413, 2025). "In summary, this study clarified that IL-8-derived tumor cells could upregulate ALDH1A1 expression by activating the NF-κB signaling pathway, promoting tumor progression." (PMID 40008905, 2025). "In addition to IGFBP7, the remaining differential genes (SDC2, COL8A1, IFI27, and ALDH1A1) were related to tumor drug resistance in the intersection of drug resistance differential genes." (PMID 40224214, 2025). "Our research indicated that ALDH1A1 plays a tumor-promoting role in ICC." (PMID 40008905, 2025).
tumor (continued). "While blocked IL-8 function by CXCR2i could detriment the tumor-promoting effect of ALDH1A1, accompanied by the changes in NF-κB." (PMID 40008905, 2025). "This indicates that the nanocomplex induced tumor cell death by DE-mediated (ALDH1A1 inhibition and caspase 3 activation) apoptosis as well as through the accumulation of Fe ONPs and DE-stimulated (lipid peroxidation overgeneration with suppressing antioxidant system) ferroptosis." (PMID 39888413, 2025). "The median expression of ALDH1A1 in tumor cells was 90.53%, with a range of 0.00 to 99.75%." (PMID 39744576, 2025). "IL-8 could upregulate ALDH1A1 expression by activating the NF-κB signaling pathway, promoting tumor progression." (PMID 40008905, 2025). "ALDH1A1 can also enhance the resistance of tumor cells to cisplatin and PARP inhibitors." (PMID 40093000, 2025). "Upregulation of ALDH1A1 could activate NF-κB to promote IL-8 secretion, forming a positive feedback loop to promote tumor invasiveness and cell stemness in ICC." (PMID 40008905, 2025). "IL-8-derived tumor cells could upregulate ALDH1A1 expression by activating the NF-κB signaling pathway, promoting tumor progression." (PMID 40008905, 2025). "(J) Multiplexed IF staining showing that the recruitment of FOXP3 + cells toward SLC26A3high cells might induce EMT (marked with E-cadherin) and increase the stemness (marked with ALDH1A1) of tumor cells, via TGF-β pathway." (PMID 40066698, 2025). "While blocked IL-8 function by CXCR2i could detriment the tumor-promoting effect of ALDH1A1 in vivo." (PMID 40008905, 2025). "In addition, mRNA expression levels of p75NTR and ALDH1A1 were analyzed in laser-microdissected samples from the tumor center and tumor invading front in OSCC samples (n = 23)." (PMID 41228340, 2025). "In comparison to adherent cells, the tumor spheroids thus generated showed an increased expression of stem markers, such as ALDH1A1, CD44, and CD133, and core transcription factors of the human stem cell pluripotency signaling pathway, such as Oct4, Sox2, and Nanog." (PMID 39335624, 2024). "Additionally, we identified that ALDH1A1 exacerbates the immune evasion characteristics of tumor cells by modulating the ZBTB7B-glycolysis regulatory pathway." (PMID 39107297, 2024). "We aimed to determine if ALDH1A1 or CD44 could provide clinically relevant tumor-specific prognostic information to aid in counseling patients and direct potential management with ALDH1A1 targeted treatment." (PMID 38371078, 2024). "Notably, the overexpression of Aldh1a1 promoted tumor growth and decreased the overall survival of mice with tumors." (PMID 39107297, 2024). "Patient 4, with relatively low ALDH1A1 expression, experienced tumor shrinkage after treatment." (PMID 39107297, 2024). "Additionally, the ALDH1A1 high expression group exhibited elevated levels of glycolysis markers, including lactate and ATP, in tumor tissues." (PMID 39107297, 2024). "Acetaldehyde dehydrogenase 1A1 (ALDH1A1) has a key role in tumor immunity." (PMID 38243323, 2024). "In this study, a novel nomogram was established by integrating the risk score of four genes (SCD, ALDH1A1, NARS2, and NFXL1), age, Gleason score, and tumor stage, each of which was an independent prognostic factor according to the multivariate Cox regression analysis." (PMID 39335669, 2024). "Additionally, ALDH1A1 regulates the synthesis of retinoic acid, which can influence gene expression patterns involved in tumor growth." (PMID 39456547, 2024). "These interactions increase as the tumor progresses, and ALDH1A1 notably induces tumor survival." (PMID 39796106, 2024). "Tumor sections were stained for ALDH1A1 expression to study the effect of treatments on OCSCs." (PMID 38191909, 2024). "Furthermore, LASS2-knockdown pBCs formed more colonies when exposed to cisplatin and led to an expansion of CD44+ALDH1A1+ subpopulation, also enhancing the capability of tumor sphere formation." (PMID 38191448, 2024).
tumor (continued). "In tumor tissues, however, ALDH1A1+ cells are detected in both secretory epithelial cells and NECs." (PMID 39796106, 2024). "In vitro experiments and tumor formation in nude mice suggested that targeting ALDH1A1 could inhibit tumor growth." (PMID 39107297, 2024). "However, our study also revealed that the accumulation of mRNA for ALDH1A1 in tumor tissue is correlated with higher sensitivity to platinum-based chemotherapy, which is usually an indicator of a better prognosis for OC patients." (PMID 37628927, 2023). "Expression of ALDH1A1 was mainly seen in the cytoplasm of tumor cells." (PMID 36768723, 2023). "More than 10% of the tumour cells in HNSCC tumour samples expressed ALDH1A1, which was scattered as single cells or small groups of cells, whereas more than 25% of the cells expressed ALDH1A1, which was distributed as sheets or islands in FA–HNSCC tumour tissue samples." (PMID 36651035, 2023). "Furthermore, ALDH1A1 regulates both normal stem cells and tumor-initiating cells, and it is often used as a marker for stem cells." (PMID 35802560, 2022). "The research also indicated that after 36 days of therapy, the tumours’ transcriptomes showed downregulation of stem-cell-related genes such as aldehyde dehydrogenase 1A1 (ALDH1A1), NANOG, GDF3, and the embryonic pluripotency-maintaining transcription factor Forkhead box D3 (FOXD3)." (PMID 36295538, 2022). "Consequently, high radiotracer retention was measured in culture in the drug-resistant SKOV3-TRip2 tumour cells which have high ALDH1A1 expression." (PMID 35656483, 2022). "ALDH1A1 mRNA levels in 18 tumors and corresponding paired para-tumor tissues were further analyzed." (PMID 36484016, 2022). "Expression levels of ALDH1A1 were found to increase along with tumour progression." (PMID 36504325, 2022). "Since 2010, numerous studies have verified the fact that ALDH1A1 could promote tumor initiation and tumor progression." (PMID 35814382, 2022). "The expression of stemness‐related markers, including CD133, ALDH1A1, Bmi1, Oct3/4 and Nanog, was inhibited dramatically, which might be the main reason for the downregulation of cell proliferation and tumour growth capacities." (PMID 34997691, 2022). "al reported that targeting ALDH1A1 in EOC sensitized resistant tumor cells to chemotherapy." (PMID 35401749, 2022). "Aldh1a1 is one of the major aldehyde dehydrogenases (ALDH) responsible for the neutralisation of reactive oxygen species (ROS) that occur when cells are under nutritional and chemotherapeutic stress, and Aldh1a1 enhances chemoresistance, metastasis and tumour initiator capability." (PMID 35277659, 2022). "In this process, aldehyde dehydrogenase 1A1 (ALDH1A1) mediates the detoxification of aldoifosfamide to carboxyifosfamide, and modifications in this enzyme activity are known to be related to toxicity and tumour resistance." (PMID 35455734, 2022). "Additionally, for some biomarkers such as ALDH1A1 and TILs, a standardized evaluation method is still missing, while the antibodies used for PD-L1 identification depends on the type of neoplasm." (PMID 36139578, 2022). "A high ALDH1A1 expression indicates increased tumor resistance to chemo- and radiotherapy." (PMID 34572930, 2021). "However, specifically inhibiting ALDH1A1 with NCT-501 only reduced the diameter of the RTR 1306MG R6T3 tumor spheres (vs. 88.2 ± 0.1 μm, p < 0.001)." (PMID 34638842, 2021). "The expression of ARID1A impacted the biological functions, including migration, invasion and sphere formation activity, of CHOL and was confirmed to exhibit a tumour-suppressive effect through the regulation of ALDH1A1, a stemness marker, with histone acetylation." (PMID 35127746, 2021). "Moreover, the cluster of EpCAM enriched cells were also enriched for several other genes of clinical interest including APOC1, a biomarker of tumor progression, ALDH1A1, a marker of tumor cell “stemness”, and AKR1C3, a marker of doxorubicin resistance." (PMID 33989287, 2021).